DOCK6 (dedicator of cytokinesis 6)
Description:
Acts as a guanine nucleotide exchange factor (GEF) for CDC42 and RAC1 small GTPases. Through its activation of CDC42 and RAC1, may regulate neurite outgrowth (By similarity).
Synonyms: KIAA1395; ZIR1; AOS2
Tractability: PROTAC: ubiquitination databases record sites on it.
Gene: Protein-coding gene on chromosome 19 (11,199,295 to 11,262,524, reverse strand). Ensembl gene ENSG00000130158.
Subcellular location: Cytoplasm; Cytoplasm, perinuclear region
Subcellular location (Human Protein Atlas): Cytosol
Pathways (Reactome):
Signal Transduction: CDC42 GTPase cycle; RAC1 GTPase cycle
Hemostasis: Factors involved in megakaryocyte development and platelet production
Gene Ontology:
Molecular function: protein binding; guanyl-nucleotide exchange factor activity
Biological process: regulation of Rho protein signal transduction; small GTPase-mediated signal transduction
Cellular component: cytosol; cytoplasm; perinuclear region of cytoplasm
Genetic constraint (gnomAD): Loss-of-function variants: 159 observed, 208.39 expected, observed/expected ratio (o/e) 0.76, 90% interval 0.67 to 0.87. The upper end of that interval is the gene's LOEUF score, 0.87, which puts it in group 3 of 6, group 1 being the genes least tolerant of losing a copy. Missense variants: 2,563 observed, 2,682 expected, observed/expected ratio (o/e) 0.96, 90% interval 0.92 to 0.99. Synonymous variants: 1,127 observed, 1,120.4 expected, observed/expected ratio (o/e) 1.01, 90% interval 0.96 to 1.06.
Gene-disease validity (ClinGen):
ClinGen rates the evidence that DOCK6 causes each of these diseases.
Adams-Oliver syndrome (autosomal recessive): Definitive. Adams-Oliver Syndrome (AOS) is a rare disorder characterized by the combination of congenital limb abnormalities and scalp defects, often accompanied by skull ossification defects.
Homologues: Orthologues: chimpanzee DOCK6 (99% identical), macaque DOCK6 (99% identical), pig DOCK6 (96% identical), dog DOCK6 (94% identical), mouse Dock6 (92% identical), rat Dock6 (91% identical), guinea pig DOCK6 (90% identical), zebrafish dock6 (72% identical), tropical clawed frog dock6 (70% identical), Caenorhabditis elegans ced-5 (11% identical). Paralogues in human: DOCK7 (68% identical), DOCK8 (53% identical), DOCK11 (31% identical), DOCK9 (31% identical), DOCK10 (28% identical), DOCK1 (15% identical), DOCK3 (15% identical), DOCK5 (15% identical), DOCK2 (15% identical), DOCK4 (14% identical).
Diseases named in the same sentence as DOCK6 in open-access papers:
DOCK6 is named in the same sentence as 50 diseases in open-access papers, as found by Europe PMC text mining. Sharing a sentence is not in itself a finding about the gene and the disease. The quoted sentences say what the papers report.
gastric cancer (6 papers, 2018 to 2025). A primary or metastatic malignant neoplasm involving the stomach. "DOCK6 has been found to be mutated in acute myeloid leukemia and has been reported to be highly expressed in gastric cancer, correlating with tumor size, depth of invasion, lymph node metastasis, vascular invasion and pathological stage." (PMID 36611369, 2022). "Research indicates that the atypical Rho GEF DOCK6 facilitates the proliferation, migration, and invasion of gastric cancer cells while also enhancing chemo- and radio-resistance via the DOCK6/Rac1/Cdc42 axis and the DOCK6/WNT/β-catenin signaling pathway." (PMID 41188920, 2025). "It was found that DOCK6 presented overexpression in the gastric cancer tissues, and the positive expression is related to gastric cancer metastasis, indicating that the gastric cancer patients showed a poor prognosis." (PMID 37274025, 2023). "DOCK6 may promote chemotherapy and radiotherapy resistance in gastric cancer through WNT/β-catenin signaling." (PMID 36761753, 2023). "MiR-148b-3p represses gastric cancer cell metastasis by targeting the Dock6/Rac1/cdc42 axis." (PMID 35549631, 2022).
epilepsy (3 papers, 2020 to 2026). A brain disorder characterized by episodes of abnormally increased neuronal discharge resulting in transient episodes of sensory or motor neurological dysfunction, or psychic dysfunction. "Seizure activity: Epilepsy and epileptic encephalopathy have been reported as rare symptoms of AOS that are associated with the DOCK6 mutation." (PMID 33858352, 2021). "Here, we report a unique case of a child with neuro‐ichthyosis presenting with pharmacoresistant epilepsy, severe developmental delay, and ichthyosis, in whom whole exome sequencing revealed multilocus pathogenic variants including CC2D2A, ABCA12, DOCK6, and a 14q31.3–q32.11 deletion." (PMID 41550404, 2026).
diabetes (2 papers, 2020 to 2022). "Four of the nine validated lncRNAs had predicted mRNA targets related to 32 genes, of which SPOP and DOCK6 have been shown to be associated with diabetes." (PMID 33299893, 2020). "To date, there have been no studies on the putative associations between DOCK6 and diabetes or CKD." (PMID 36143124, 2022).
glioma (2 papers, 2018 to 2022). A benign or malignant brain and spinal cord tumor that arises from glial cells (astrocytes, oligodendrocytes, ependymal cells). "Glioma-associated DEGs DOCK6, ILK, MGMT, NOTCH4 were up-regulated and FGF10, JAK1, JUNB, RHOB were down-regulated uniquely in the mouse." (PMID 29352201, 2018). "This is the first study reporting DOCK6 mutations in gliomas." (PMID 36611369, 2022).
thyroid cancer (2 papers, 2023 to 2025). "DOCK6 is one of the novel age-related biomarkers for identifying and validating thyroid cancer, which can predict prognosis and immunotherapy." (PMID 40740229, 2025). "In a real-world experiment, the RT-qPCR results were consistent with the bioinformatic analysis, confirming that ADAMTSL4, DOCK6, FAM111B, and SEMA6B were expressed at higher levels in thyroid cancer cells (p < 0.05), while MRPS10 and PSMB7 were expressed at lower levels (p < 0.05)." (PMID 36761753, 2023).
atrial septal defect (1 paper, 2025). Interauricular communication is a congenital malformation characterized by a communication between the atrial chambers of the heart. "Variants in genes associated with atrial septal defects and ventricular septal defects (e.g., DOCK6, EOGT, EP300, EVC, EVC2, and SEMA3C) have also been identified in patients." (PMID 41153298, 2025).
autosomal recessive congenital ichthyosis (1 paper, 2026). Autosomal recessive form of inherited ichthyosis. "Genetic mutations in genes such as CC2D2A, ABCA12, and DOCK6 have been independently implicated in syndromic forms of Joubert syndrome, autosomal recessive congenital ichthyosis (ARCI), and Adams‐Oliver syndrome, respectively." (PMID 41550404, 2026).
ciliopathy (1 paper, 2026). A genetic disorder of the cellular cilia or the cilia anchoring structures, the basal bodies, or of ciliary function. "The phenotype is primarily driven by CC2D2A‐related ciliopathy, with ABCA12, DOCK6 variants, and the 14q31.3–q32.11 deletion acting as likely genetic modifiers." (PMID 41550404, 2026).
coronary heart disease (1 paper, 2023). "Variants of DOCK6 have been associated with GWAS studies on coronary heart disease and total and HDL cholesterol levels." (PMID 37679740, 2023).
diabetic nephropathy (1 paper, 2022). "Interestingly, we found a significant haplotype association between DOCK6 rs17699089_rs737337 and diabetic nephropathy." (PMID 36143124, 2022). "The DOCK6 rs17699089G_rs737337C haplotype was positively associated with diabetic nephropathy." (PMID 36143124, 2022). "Another tested DOCK6 variant, rs17699089, was not directly associated with mortality or diabetic nephropathy in the entire group of Polish HD subjects." (PMID 36143124, 2022).
Epileptic spasm (1 paper, 2022). A sudden flexion, extension, or mixed extension-flexion of predominantly proximal and truncal muscles that is usually more sustained than a myoclonic movement but not as sustained as a tonic seizure. "In this series, 8/36 patients (22.2%) had epileptic spasms, including those with KCNT1, SCN2A, SCN1A, DOCK6 and PCDH19 variants." (PMID 35715422, 2022).
Hypsarrhythmia (1 paper, 2022). Hypsarrhythmia is abnormal interictal high amplitude waves and a background of irregular spikes. "Vitamin B6 allowed patients with ALDH7A1 and PNPO mutations to achieve seizure-free status, oxcarbazepine was effective for patients with SCN2A, ATP7A, WWOX, and PRRT2 mutations, and ACTH was partly effective for DOCK6 mutation patients with spasms and hypsarrhythmia." (PMID 35715422, 2022). "ACTH was partly effective for patients with DOCK6 mutations who had spasms and hypsarrhythmia." (PMID 35715422, 2022).
ichthyosis (1 paper, 2026). Disorders of cornification that are characterized by visible scaling and/or hyperkeratosis of most or all of the skin. "Unlike classic Joubert syndrome, this patient had profound developmental regression and ichthyosis, suggesting modifying effects from ABCA12, DOCK6, and the 14q deletion." (PMID 41550404, 2026).
intrauterine growth restriction (1 paper, 2018). "We also noted a positive correlation between patients with recessive mutations in DOCK6 and the presence of neurological abnormalities, intrauterine growth restriction, or ocular anomalies." (PMID 29924900, 2018).
Joubert syndrome type 9 (1 paper, 2026). "Whole exome sequencing identified a homozygous CC2D2A variant consistent with Joubert syndrome type 9, along with heterozygous variants in ABCA12 and DOCK6, and a 14q31.3–q32.11 deletion." (PMID 41550404, 2026).
lymph node metastasis (1 paper, 2018). "Positive Dock6 expression was associated with gender, lymph node metastasis and a higher TNM stage." (PMID 29587866, 2018).
microcephaly (1 paper, 2021). A congenital or acquired developmental disorder in which the circumference of the head is smaller than normal for the person's age and sex. "We proposed that mutation of DOCK6 and ARHGAP31 genes could be the possible cause of FEVR associated with microcephaly." (PMID 33655927, 2021).
migraine (1 paper, 2023). "Remaining genes differentially methylated in migraine were kinesin family member 26A (KIF26A), dedicator of cytokinesis 6 (DOCK6), and complement factor D (CFD) that were reported to associate with various aspects of the aging process." (PMID 37199585, 2023).
myocardial infarction (1 paper, 2022). Gross necrosis of the myocardium, as a result of interruption of the blood supply to the area, as in coronary thrombosis. "IGFBP3 rs3110697, DOCK6 rs737337, and DOCK6 rs17699089 showed a gene–gene interaction concerning the diagnosis of myocardial infarction (TBA 0.63, p-value 0.032)." (PMID 36143124, 2022). "In our study, DOCK6 rs737337 and rs17699089 interacted with IGFBP3 rs3110697 in relation to myocardial infarction diagnosis among HD patients." (PMID 36143124, 2022).
non-small cell lung carcinoma (1 paper, 2022). A group of at least three distinct histological types of lung cancer, including non-small cell squamous cell carcinoma, adenocarcinoma, and large cell carcinoma. "The intersection of the two was taken to screen five non-small cell lung cancer signature genes from the training sets GSE151103 and GSE33532: DOCK6, GPC2, RHEBL1, RNPC3, and PIWIL2." (PMID 36386821, 2022).
infection (8 papers, 2017 to 2025). The state of being infected such as from the introduction of a foreign agent such as serum, vaccine, antigenic substance or organism. "SGC-7901NM-Dock6-OE cells were then established by Lenti-Dock6 infection, and SGC-7901 M-Dock6-KD cells were established by infection with a lentivirus expressing Cas9 and Dock6-sgRNA, and the Dock6 protein expression levels in these cell lines were then detected by western blot." (PMID 29587866, 2018).
tumor (3 papers, 2018 to 2023). "Recurrent tumor presented the following set of mutations: H3F3A (c.344C > G; p.Ala115Gly), PIK3CA (c.2119G > A; p.Glu707Lys), NF1 (c.7026G > T; p.Leu2342=) and DOCK6 (c.1664C > T; p.Pro555Leu)." (PMID 36611369, 2022). "The validation part demonstrated that ADAMTSL4, DOCK6, FAM111B, and SEMA6B were expressed at higher levels in the tumor tissue, whereas lower expression of MRPS10 and PSMB7 was observed." (PMID 36761753, 2023).
bone disorder (1 paper, 2022). "Rare variants of the DOCK6 gene have never been reported in patients with bone disorders in the literature and its expression in osteoclasts is unknown." (PMID 35241069, 2022).
DOCK6 also shares sentences with these, for which no sentence is quoted: Adams-Oliver syndrome (5 papers); aplasia cutis congenita (2); 22q11.2 deletion syndrome (1); acute myeloid leukemia (1); axonal neuropathy (1); bacterial infection (1); Beckwith-Wiedemann syndrome (1); cancer (1); cortical dysplasia (1); cyst (1); developmental delay (1); Epileptic encephalopathy (1); esophageal squamous cell carcinoma (1); fungal infection (1); glioblastoma (1); heart failure (1); Intellectual disability (1); Jacobsen syndrome (1); Joubert syndrome (1); Kabuki syndrome (1); Lissencephaly (1); lung carcinoma (1); Niemann-Pick disease (1); Paget’s disease of bone (1); Stroke (1); Turner syndrome (1); ventricular septal defect (1).